CXCL12 (C-X-C motif chemokine ligand 12)
Diseases named in the same sentence as CXCL12 in open-access papers (continued):
Sharing a sentence is not in itself a finding about the gene and the disease.
breast carcinoma (continued). "To confirm that CXCL12 expression can produce such effects, we overexpressed CXCL12 in MTLn3 breast cancer cells and observed increased in vivo invasion as well as increased tumor-associated macrophage recruitment." (PMID 22314082, 2012). "Our data reveal a physiological trigger for DIP-directed mDia2-dependent blebbing in mesenchymal breast cancer cells- CXCL12- which stimulates blebbing both in 2D and 3D matrices, while driving the assembly of the DIP:mDia2 complex to blebs." (PMID 23024796, 2012). "CXCL12 is normally constitutively generated by stroma, but it is downregulated when breast cancer cells contact stroma." (PMID 22482060, 2012). "The dimeric CXCL12 activates recruitment of β-arrestin 2 to CXCR4 and chemotaxis of CXCR4-expressing breast cancer cells, whereas the monomeric CXCL12 promotes the CXCR4 signaling through Gαi and Akt." (PMID 22807925, 2012). "In particular, high levels of functional CXCR4 receptors have been observed on human breast cancer cells and correspondingly, the highest CXCR4 ligand expression, CXCL12, was detected in organs that are preferential destinations of breast cancer metastasis." (PMID 22433180, 2012). "The CXCR4 chemokine together with its ligand, CXCL12, are involved in the mechanism of breast cancer metastasis." (PMID 22220212, 2011). "The chemokine CXCL12 (also named SDF-1 for Stromal-cell Derived Factor 1) was identified as a key mediator of E2-induced breast cancer cell proliferation and survival." (PMID 21695171, 2011). "Concordantly, an elevated migratory signaling response to ectopic CXCL12 was also shown to contribute to the metastatic potential of CXCR4-expressing mammary carcinoma cells, subsequent to epigenetic silencing of autocrine CXCL12." (PMID 21349176, 2011). "CXCR4/CXCL12 signaling axis has been shown to promote migration and invasion of breast cancer cells to distant sites of metastasis such as the lung, brain, bone, lymph nodes, and liver." (PMID 21915267, 2011). "Breast cancer cells from primary tumors over-expressing CXCR4 are attracted to CXCL12 expressing cells in the lung, lymph nodes, liver or bones, which leads to the metastasis of detached tumor cells." (PMID 22220212, 2011). "Recent studies have assessed the prognostic significance of CXCL12 expression in various cancers, including colorectal carcinoma, pancreatic ductal adenocarcinoma, breast cancer, esophageal squamous cell carcinoma, endometrial cancer, germ cell tumors and EOC." (PMID 21410972, 2011). "CXCR4 and CXCR7 are the two receptors for the chemokine CXCL12, a key mediator of the growth effect of estrogens (E2) in estrogen receptor (ER)-positive breast cancers." (PMID 21695171, 2011). "Our results show that CB2 agonist JWH-015 significantly inhibits CXCL12-induced cell migration and wound healing in breast cancer cells." (PMID 21915267, 2011). "CXCL12 has been shown to induce various signaling pathways including p44/p42 ERK in breast cancer and other cell types." (PMID 21915267, 2011). "On a log rank test, positive CXCL12 expression correlated with longer breast cancer-specific survival (P = 0.024)." (PMID 21521526, 2011). "We, therefore, investigated CXCR4 expression in Treg, together with the expression of CA9 and CXCL12 in basal-like and other subtypes of breast cancers." (PMID 21521526, 2011). "CXCR4 and its cognate ligand CXCL12 have been shown to play an important role in regulating metastasis of breast cancer to specific organs." (PMID 21915267, 2011). "Stromal cells in all of these sites have been shown to highly express CXCL12 and were able to induce chemotaxis and invasion of breast cancer cells in vitro." (PMID 24212798, 2011). "We have shown that JWH-015 inhibits CXCL12-induced phosphorylation of p44/p42 ERK in breast cancer cells." (PMID 21915267, 2011). "The chemokine CXCL12 is thought to mediate the growth effect of E2 in ER-positive ovary and breast cancer cells." (PMID 21695171, 2011).
breast carcinoma (continued). "Here, we report for the first time that CB2 specific synthetic agonist inhibits CXCL12-induced migration and invasion of breast cancer cell lines in vitro." (PMID 21915267, 2011). "Primary human breast cancer cells can also respond to CXCL12 and in breast cancer patients, high levels of CXCR4 expression have been correlated with lymph node metastasis in invasive ductal carcinoma and associated with poor overall survival." (PMID 24212798, 2011). "This group studied CXCL12 mRNA levels of 10 primary breast cancer tumors along with their matching lymph node metastases and observed CXCL12 levels to be higher in lymph node tumors than the primary breast tumor (P < 0.001)." (PMID 22295222, 2011). "This study provides novel insights about anti-tumorigenic effects of CB2 receptors in breast cancer through modulation of CXCR4/CXCL12 signaling axis." (PMID 21915267, 2011). "This suggests a privileged homing, survival and proliferation of metastatic breast cancer cells to these specific sites, where the local secretion of CXCL12 is strong." (PMID 21695171, 2011). "We analyzed the effect of JWH-015 on CXCL12-induced focal adhesion formation and actin stress fiber formation in various breast cancer cell lines." (PMID 21915267, 2011). "Immunoperoxidase staining for FOXP3 and CXCL12 was performed on tissue microarrays from 491 breast cancers." (PMID 21521526, 2011). "That study showed an inverse relationship between CXCL12 expression levels and disease-free and overall survival in breast cancer patients." (PMID 22295222, 2011). "In this study we examined E2-regulation of the CXCL12 axis components and their involvement in the growth of breast cancer cells." (PMID 21695171, 2011). "In conclusion, our study demonstrated that the components of the entire CXCL12 signaling axis are targeted by E2 in breast cancer cells." (PMID 21695171, 2011). "CXCL12 is expressed at high levels in the bone marrow, lung, liver, and lymph nodes, common sites of breast cancer metastasis, with protein extracts from these organs stimulating chemotaxis of breast cancer cells in a CXCR4-dependent manner." (PMID 22152016, 2011). "We also observed that JWH-015 inhibits CXCL12-induced focal adhesion formation along with a decrease in actin stress fibers in breast cancer cells." (PMID 21915267, 2011). "The regulation of CXCL12 expression by promoter hypermethylation is common in colon carcinoma and breast cancer, suggesting that tumour cells that silence CXCL12 are at a selective advantage for metastasis." (PMID 20109227, 2010). "Epigenetic silencing of CXCL12 has been shown to increase the metastatic potential of mammary carcinoma cells." (PMID 20830311, 2010). "A growing body of work implicates chemokines, in particular CXCL12 and its receptors, in the progression and site-specific metastasis of various cancers, including breast cancer." (PMID 20849618, 2010). "In this respect, a very extensive research was performed on CXCL12/CXCR4 ligand/receptor pair in breast cancer, showing high expression of CXCL12 in target metastatic organs of breast tumor cells, and the expression of CXCR4 in tumor cells." (PMID 20049170, 2010). "Secretion of stromal cell-derived factor-1 (SDF-1)/CXCL12 and expression of CXCR4 have been identified to be associated with breast cancer metastasis." (PMID 20652010, 2010). "Kochetkova and colleagues showed that transient CXCL12 stimulation increased tumor metastasis by inhibiting anoikis through induction of Bmf and Bcl-XL anti-apoptotic proteins in breast cancer cells." (PMID 20877573, 2010). "In this study, we assessed the epigenetic regulation of the CXCL12 and ESR1genes in breast cancer samples from Brazilian women." (PMID 20109227, 2010).
breast carcinoma (continued). "Muller demonstrated that CXCR4 is consistently expressed in human breast cancer cells, malignant breast tumor and metastasis tumors, while its ligand CXCL12 is preferentially expressed in the lungs, liver, bone marrow, and lymph nodes." (PMID 20181250, 2010). "The CXCR4/CXCL12 (SDF-1) axis was the most common interaction that has been shown to be involved in many different human malignancies, including breast cancer, ovarian cancer, and prostate cancer." (PMID 20652010, 2010). "The inhibitory effects of CXCL12 on primary tumor growth were confirmed in the EMT6.5 syngeneic mouse model of breast cancer." (PMID 20849618, 2010). "According to previous studies, invasion of CXCR4-expressing breast cancer cells is enhanced in response to SDF-1/CXCL12." (PMID 21167057, 2010). "In this study we have shown that a novel antagonist of CXCR4, a mutant form of the natural ligand, CXCL12, is capable of blocking the spontaneous metastasis of breast cancer cells from the primary tumor in an orthotopic mouse model of breast cancer." (PMID 20849618, 2010). "It has been demonstrated that the CXCR4/CXCL12 axis likewise induces chemotaxis and breast cancer cell migration." (PMID 20181250, 2010). "Other studies have demonstrated that CXCL12 transactivates HER2 in breast cancer cells, enhancing the expression of CXCR4 and favouring metastases." (PMID 20946648, 2010). "Antitumor efficacy of AMD3100 was demonstrated in breast cancer where it blocks CXCL12-induced HER2/neu activation in vitro and inhibits tumor growth in vivo." (PMID 20049170, 2010). "In contrast to mammary carcinomas stimulated with exogenously added CXCL12, we determined that re-establishment of CXCL12 expression characteristic of the normal epithelium increases anoikis sensitivity of colorectal carcinoma cells." (PMID 20877573, 2010). "It is noteworthy that a recent study has shown that expression of CXCL12 in breast cancer tissues significantly correlates with disease-free and overall survival." (PMID 20849618, 2010). "CXCL12 is also an angiogenic chemokine and CXCL12 secretion by fibroblasts co-implanted into nude mice with breast carcinoma cells promotes vascularization of the developing tumors." (PMID 20849618, 2010). "To establish the utility of this microfluidic device for studying intravascular steps in metastasis, we investigated effects of chemokine CXCL12 on adhesion of circulating breast cancer cells to endothelium." (PMID 19484126, 2009). "We have shown previouslythat DIM lowers the levels of CXCR4 and CXCL12, a chemokine receptor and itsunique ligand required for the metastasis of breast cancer." (PMID 19325924, 2009). "CXCR4 is known to be upregulated in breast tumors; neutralizing the interaction of CXCL12 with CXCR4 significantly reduces breast cancer cell metastases in vivo, as does the repression of CCL5 that has anti-migratory effects." (PMID 19123925, 2009). "The activation of a paracrine loop CXCR4/CXCL-12 involving tumor cells and stromal fibroblasts induces tumor growth in implants of MCF-7 breast carcinoma cells with cancer associated fibroblasts (CAF)." (PMID 19226458, 2009). "Müller and colleagues provided initial evidence linking CXCL12/CXCR4 biological axis to breast cancer metastasis to specific organs, which was confirmed in non-small lung cancer." (PMID 19563666, 2009). "Using the microfluidic vasculature to selectively manipulate cancer cells and endothelium, we demonstrate that circulating breast cancer cells preferentially adhere to endothelium stimulated from the basal side with CXCL12." (PMID 19484126, 2009). "T140 analogs inhibited in dose-dependent manners the migration of a CXCR4-positive human breast carcinoma cell line MDA-MB-231 induced by CXCL12." (PMID 19787093, 2008). "Organs that are the first destination of breast cancer metastases have high levels of CXCL12, the CXCR4-specific ligand." (PMID 18941460, 2008).
breast carcinoma (continued). "When indicated, the chemoattractant CXCL12 was added in the bottom chamber to induce CXCR4-positive breast cancer cell to invade through the Matrigel (specific chemoinvasion)." (PMID 18941460, 2008). "This 50-set also contains genes previously linked to breast cancer prognosis, metastasis or treatment response (BCL2, CXCL12 and FBLN1)." (PMID 19094230, 2008). "In preliminary experiments, we found that CXCL12 induced the migration of breast cancer cells through Matrigel in a dose-dependent manner." (PMID 18941460, 2008). "Such stromal myofibroblasts, present in invasive human breast carcinomas were demonstrated to promote tumor growth and angiogenesis through elevated SDF-1/CXCL12 secretion." (PMID 19002260, 2008). "More specifically, recent evidence suggests that the CXCR4/CXCL12 axis plays an integral role in guiding metastatic cells from breast carcinoma." (PMID 17261188, 2007). "These oligosaccharides also significantly inhibited CXCL12-induced migration of CXCR4-expressing LMD MDA-MB 231 breast cancer cells." (PMID 17726466, 2007). "In vivo studies have confirmed the importance of CXCL12/CXCR4 interactions in breast cancer metastasis." (PMID 17726466, 2007). "It was found that the migration of breast cancer cells across transmembrane filters towards 12.5 nM CXCL12 was significantly inhibited in the presence of 25 μg ml−1 (7 μM) of the dp12 oligosaccharide (P<0.001)." (PMID 17726466, 2007). "Expression of the chemokine receptor CXCR4 allows breast cancer cells to migrate towards specific metastatic target sites which constitutively express CXCL12." (PMID 17726466, 2007). "Following definition of dp12 as the shortest oligosaccharide to significantly bind CXCL12, this size pool was assayed for its effect on breast cancer cells in vitro." (PMID 17726466, 2007). "The current study confirmed these observations by demonstration that dp12 inhibits the migration of breast cancer cells towards CXCL12 in vitro." (PMID 17726466, 2007). "It is now thought that the metastasis of breast cancer cells is driven by the presentation of CXCL12 by heparan sulphate on the vascular endothelium and ECM." (PMID 17726466, 2007). "Müller and colleagues provided initial evidence linking the CXCL12/CXCR4 biological axis to breast cancer metastasis to specific organs, which was confirmed in non-small cell lung cancer." (PMID 17083723, 2006). "The role of CXCL12/CXCR4 axis in organ-specific metastasis was initially suggested in breast cancer." (PMID 17083723, 2006). "Chemokine receptor CXCR4 was found to be involved in HIV infection and was highly expressed in human malignant breast tumors and the ligand for CXCR4, CXCL12 (SDF-1), exhibited high expression in organs in which breast cancer metastases are often found." (PMID 15978137, 2005). "CXCL12 expression was higher in breast cancer metastasis organs, normal lymph nodes, bone marrow, liver and lung, compared to skin, a site of low metastasis frequency, as described." (PMID 16189523, 2005). "On the other hand CXCL12 exhibited peak levels of expression in organs representing the first destinations of breast cancer metastasis, i.e. lymph nodes, lung, liver and bone marrow." (PMID 11953881, 2002). "Similarly, in breast cancer, iCAFs recruit Tregs and induce an immunosuppressive microenvironment through the CXCL12/CXCR4 axis, ultimately contributing to resistance to anti‐PD‐1 therapy." (PMID 41164803, 2025). "HIF also induces high CXCL12/CXCR4 responsible for breast cancer progression and metastasis." (PMID 40076892, 2025). "Furthermore, the CXCL12/SDF‐1 chemokine produced by CAFs is instrumental in driving the metastasis of CXCR4‐expressing breast cancer cells specifically to the lymph nodes and lungs." (PMID 40150879, 2025). "Research has shown estradiol regulation of the CXCL12 axis in the growth of breast cancer cells." (PMID 40182431, 2025).
breast carcinoma (continued). "Furthermore, a metanalysis showed a positive prognostic role for SDF1/CXCL12 in breast cancer, with its overexpression correlated with better prognosis in terms of both disease-free survival and overall survival of breast cancer." (PMID 39859358, 2025). "In addition, the chemokine receptor CXCR4 was highly expressed in breast cancer tissues, and its ligand CXCL12 was overexpressed in common metastatic sites of breast cancer including bone marrow." (PMID 39605887, 2024). "Blocking the CXCL12/CXCR4 pathway may suppress the growth of breast cancer cells by reducing the expression of proteins that facilitate the G2-M phase transition (PLK1, Myt1, and cyclin B1), and then disrupting mitotic processes." (PMID 39703847, 2024). "Furthermore, other studies have suggested that high levels of CXCL12 expression are often found in patients with breast cancer lymph node and brain metastases, which correlates with poorer overall survival." (PMID 39703847, 2024). "In breast cancer, loss of SLIT/ROBO signaling may decrease the phosphorylation of downstream CXCL12/CXCR4 molecules, increase GSK-3β phosphorylation, and influence the expression and distribution of β-catenin." (PMID 39479352, 2024). "In addition, astrocytes in the brain are capable of promoting the metastatic transformation of circulating breast cancer cells and localizing them to the brain through secretion of chemokine CXCL12." (PMID 37307835, 2024). "Interestingly, recent investigations have revealed that overexpression of CXCL12 in MCF7 cell lines (Breast cancer) leads to upregulation of OCT4, Nanog, and SOX2." (PMID 39070795, 2024). "CXCL12 was shown to transactivate HER2-neu in the breast cancer cell lines MDA-MB-361 and SKBR3, which express both CXCR4 and HER2-neu that was inhibited by AMD3100, a CXCR4 inhibitor, PKI 166, an epidermal growth factor receptor/HER2- tyrosine kinase inhibitor, and PP2, a Src kinase inhibitor." (PMID 39001456, 2024). "In addition, IL-1B from MDA-MB-231 cells activated mesenchymal stem cells, leading to the induction of CXCL-12, which, in turn, promoted the trans-endothelial migration of these breast cancer cells into the bone." (PMID 38800348, 2024). "Moreover, CXCL12 induction occurs only in AR-positive breast cancer cell lines, via an androgen response element (ARE) upstream of the CXCL12 promoter." (PMID 38338982, 2024). "Altogether, CXCL12 may provide a potential therapeutic target for breast cancer, which could pave the way for innovative approaches to breast cancer therapies." (PMID 39703847, 2024). "The CXCL12-related prognostic model could well predict the prognosis and treatment response of breast cancers." (PMID 37564657, 2023). "CAFs and chemokine CXCL12 are the most often studied in the invasive progression of breast cancer." (PMID 37978384, 2023). "However, CAF-S1 and CAF-S4 subsets secrete TGFβ and CXCL12 to activate NOTCH signaling and have been associated with TNBC and HER2+ breast cancers, respectively." (PMID 36793444, 2023). "After multiple additional validation cohorts, we demonstrated that this CXCL12-related signature could predict the prognoses of breast cancers." (PMID 37564657, 2023). "Conducting a comprehensive study using multi-omics data including bulk transcriptomics and genomics, scRNA-seq, snRNA-seq and spatial transcriptomics, we systematically unearthed the immunological implication and prognostic significance of CXCL12 in breast cancer." (PMID 37564657, 2023). "Relevant studies have shown that the high expression of CXCL12 could promote drug resistance in pancreatic cancer, breast cancer, and acute lymphoblastic leukaemia." (PMID 38057830, 2023). "CXCL12 has important immunological implication and prognostic significance in breast cancer." (PMID 37564657, 2023). "Various breast cancer cell lines expressing HER2 were incubated for 24 h with CXCL12–Tras." (PMID 36138170, 2023).